OGG1 (8-oxoguanine DNA glycosylase)
Diseases named in the same sentence as OGG1 in open-access papers (continued):
Sharing a sentence is not in itself a finding about the gene and the disease.
bipolar disorder (4 papers, 2012 to 2025). A disorder of the brain that causes unusual shifts in mood, energy, activity levels and the ability to carry out day-to-day tasks. "Intriguingly, BER has been implicated in bipolar disorder, with studies showing that OGG1 is downregulated in a cohort of bipolar disorder patients." (PMID 40779073, 2025). "In contrast, a study reported decreased OGG1 gene expression in acute unipolar or bipolar depression compared to HCs, with a significant increase after remission." (PMID 38789433, 2024). "After Bonferroni correction, POLG (P=0.001) and OGG1 (P=0.001) remained significantly downregulated in bipolar disorder patients." (PMID 26241352, 2015). "We found downregulation of POLG and OGG1 expression in bipolar disorder patients compared with healthy control subjects." (PMID 26241352, 2015). "We found downregulation of two genes, POLG and OGG1, in bipolar disorder patients compared with healthy control subjects after correction for multiple testing and adjusting for possible confounders." (PMID 26241352, 2015). "Although the association with bipolar disorder was significant for DEG sets of single KOs and DKO, the most pronounced enrichment occurring in NeuN- nuclei of DKO, suggesting an additive effect resulting from the simultaneous depletion of Ogg1 and Mutyh." (PMID 40779073, 2025). "In addition, we demonstrated aberrant regulation of the POLG, NDUFV2 and, for the first time, the OGG1 gene, pointing to disturbances within mitochondrial function and DNA damage repair mechanisms as pathophysiological mechanisms in bipolar disorder." (PMID 26241352, 2015). "OGG1 expression dysregulation is a novel finding in bipolar disorder." (PMID 26241352, 2015). "The present findings of altered POLG, OGG1 and NDUFV2 expression point to disturbances within mitochondrial function and DNA repair mechanisms in bipolar disorder." (PMID 26241352, 2015). "The effect of medication on OGG1 and POLG expression in bipolar disorder patients in vivo has not previously been investigated." (PMID 26241352, 2015).
colorectal adenoma (4 papers, 2006 to 2022). An adenoma that arises from the colon or rectum. "Previously, we reported a reduced risk of colorectal adenomas and cancer in association with another BER gene polymorphism, the OGG1 Ser326Cys." (PMID 16542436, 2006). "Moreover, we observed evidence that SNPs in other BER genes modified the effect of smoking (MUTYH, OGG1), alcohol (LIG3), and dietary folate (LIG3) on colorectal adenoma risk." (PMID 23951112, 2013). "In conclusion, mRNA levels of ERCC1 and OGG1 were up-regulated in both colorectal adenomas and carcinomas compared to corresponding normal colonic mucosa, indicating that increased expression of defense genes is an early event in the progression of colorectal adenomas to CRC." (PMID 16914027, 2006). "In this study we have measured mRNA levels of ERCC1, OGG1 and RAI in patients with colorectal adenomas and carcinomas (normal colonic mucosa and lesions)." (PMID 16914027, 2006).
dementia (4 papers, 2014 to 2025). Loss of intellectual abilities interfering with an individual's social and occupational functions. "On the other hand, in patients with TOMM40’523 S/S genotype, most likely reduced the efficiency of the oxidative damage repair system (OGG1) led to the accumulation of oxidative damage in DNA and early symptoms of dementia." (PMID 30443289, 2018). "However, as demonstrated in our previous report, in particular, when looking at the stage of AD during which the disease progressed from mild to moderate dementia, there was an increase in the OGG1 protein level along with the increase of oxidative DNA damage." (PMID 40004097, 2025). "In turn, in the present study we observed a reverse tendency for increase of OGG1 level in plasma of AD patients, what could be a response to the CNS DNA damage, as a consequence of the ongoing dementia process and the late activation of repair mechanisms." (PMID 30443289, 2018). "We compared the gene expression of APE1, OGG1, Polβ and PARP1 in 41 AD patient with dementia, 28 patients with MCI due to AD pathology, 45 patients with MCI and 24 patients with SCI and 28 HC." (PMID 27234294, 2016).
head and neck squamous cell carcinoma (4 papers, 2013 to 2020). A squamous cell carcinoma that arises from any of the following anatomic sites: lip and oral cavity, nasal cavity, paranasal sinuses, pharynx, larynx, and salivary glands. "OGG1 activity was found lower in leukocytes and lung tumor tissues of NSCLC60–63, and leukocytes of squamous cell carcinoma of head and neck (SCCHN) cancers." (PMID 33004944, 2020).
Hyperglycemia (4 papers, 2014 to 2024). An increased concentration of glucose in the blood. "However, little is known about whether hyperglycemia can aggravate bupivacaine-induced DNA damage and whether hyperglycemia is associated with OGG1 expression in response to DNA damage when diabetic patients receive nerve block anesthesia." (PMID 26161242, 2015). "A previous study showed that Ogg1-KO mice fed a normal diet ad libitum exhibited hyperglycemia, elevated insulin levels, higher liver glycogen content, and inefficient suppression of gluconeogenesis." (PMID 39596235, 2024). "Chronic hyperglycemia leads to phosphorylation/inactivation of tuberin and downregulation of OGG1 via a redox-dependent activation of akt, resulting in accumulating cell DNA damage." (PMID 26161242, 2015). "Hyperglycemia can inhibit expression of the 8-oxoG-DNA glycosylase (OGG1) which is one of the key repair enzymes for DNA oxidative damage." (PMID 26161242, 2015). "Previous study has reported that chronic hyperglycemia could inhibit OGG1 expression via a redox-dependent activation of akt, resulting in accumulating cell DNA damage." (PMID 26161242, 2015). "The effect of hyperglycemia on OGG1 expression in response to local anesthetics-induced DNA damage is unknown." (PMID 26161242, 2015). "Our findings may provide a model that is useful for exploring the molecular mechanisms of OGG1 involvement in chronic hyperglycemia-aggravated neurotoxicity in diabetic patients treated with bupivacaine." (PMID 26161242, 2015). "It suggested that antioxidant could reverse hyperglycemia-induced inhibitory effect on OGG1." (PMID 26161242, 2015).
kidney clear cell carcinoma (4 papers, 2008 to 2022). "Loss of heterozygosity at the OGG1 allele, located on chromosome 3p25, is found in 85% of 99 human kidney clear cell carcinoma samples, identifying loss of OGG1 function as a possible consequence of multistep carcinogenesis in the kidney." (PMID 19265534, 2009). "Loss of heterozygosity at the OGG1 allele was found in human kidney clear cell carcinoma, identifying loss of OGG1 function as a possible consequence of multistep carcinogenesis in the kidney." (PMID 19265534, 2009). "Loss of heterozygosity at the 8-oxoG-DNA glycosylase (OGG1) allele is found in human kidney clear cell carcinoma identifying loss of OGG1 function as a possible contributor to tumorigenesis in the kidney." (PMID 19265534, 2009). "Loss of heterozygosity at the OGG1 allele, located on chromosome 3p25, was found in 85% of 99 human kidney clear cell carcinoma samples, identifying the loss of OGG1 function as a possible consequence of multistep carcinogenesis in the kidney." (PMID 18218111, 2008). "Moreover, loss of heterozygosity at the OGG1 allele is found in 85% of 99 human kidney clear cell carcinoma samples, identifying that loss of OGG1 function as a possible consequence of multistep carcinogenesis in the kidney." (PMID 20040097, 2009). "Loss of function mutations of OGG1 also occurs in human kidney clear cell carcinoma and may contribute to tumorgenesis." (PMID 18218111, 2008).
lymphoma (4 papers, 2017 to 2021). A malignant (clonal) proliferation of B- lymphocytes or T- lymphocytes which involves the lymph nodes, bone marrow and/or extranodal sites. "Previously, Myh and Ogg1 knockout mice were demonstrated to develop spontaneously lymphomas and lung and ovary tumors." (PMID 28785378, 2017). "At week 38, the first PB-treated Ogg1+/+ male mouse with a malignant lymphoma was found." (PMID 28785378, 2017).
nasopharyngeal carcinoma (4 papers, 2014 to 2021). A carcinoma arising from the nasopharyngeal epithelium. "Several studies suggest that individuals carrying OGG1 326 Cys/Cys genotype have a higher risk of lung, prostate and nasopharyngeal cancer." (PMID 25526641, 2014). "Furthermore, OGG1-rs1052133 polymorphism has been implicated in the pathogenesis of nasopharyngeal carcinoma (NPC), especially among women: genotype GG at rs1052133 was associated with significantly lower NPC risk than genotypes GC + CC OR: 0.770, 95% CI: 0.595–0.996, p = 0.012)." (PMID 32192442, 2020).
neuroblastoma (4 papers, 2018 to 2024). Neuroblastoma (NB) is the most common solid, extracranial childhood tumor. "We show that neuroblastoma tumors with high C > A substitution frequencies were enriched for copy number loss (CNL) of OGG1 and MUTYH." (PMID 34479993, 2021). "Other neuroblastoma tumors indicate that partial loss of OGG1 or MUTYH can also be sufficient to induce high C > A substitution levels." (PMID 34479993, 2021). "In a neuroblastoma tumor (N701T) with one of the highest C > A mutation frequencies, a germline OGG1 missense variant was identified." (PMID 34479993, 2021). "Most neuroblastoma tumors show heterozygous loss instead of homozygous loss of OGG1 or MUTYH, which we expect to result in a similar but more modest phenotype." (PMID 34479993, 2021). "To test, wild type, knockout, siRNA-depleted MEFs and neuroblastoma cells, or those expressing repair-deficient OGG1 mutants were oxidatively stressed and the role of OGG1 was examined." (PMID 29795387, 2018). "Additionally, missense mutations and loss-of-heterozygosity in Ogg1 have been associated with increased risk of human cancer, and copy-number losses of either Ogg1 or Mutyh are linked to elevated rates of spontaneous C>A mutation in human neuroblastoma." (PMID 38381482, 2024). "To test whether this mutation in OGG1 is indeed inactivating, we also induced overexpression of OGG1 containing the missense variant (p.G308E) in the neuroblastoma cell line with OGG1 CNL." (PMID 34479993, 2021). "In clustering analysis, these clones group together with neuroblastoma tumors with OGG1 or MUTYH CNL." (PMID 34479993, 2021). "We used CRISPR-Cas9 genome editing to create knockout clones of MUTYH and OGG1 in neuroblastoma cells." (PMID 34479993, 2021). "Overall, these results indicate that the OGG1 and MUTYH knockout clones have a high contribution of C > A mutational signatures 18 and 36, respectively, and cluster together with neuroblastoma tumors with OGG1 or MUTYH CNL." (PMID 34479993, 2021). "To show that the increased levels of 8-oxoG are indeed caused by the defects in OGG1 and MUTYH, we performed rescue experiments by inducing overexpression of wild-type OGG1 or MUTYH in neuroblastoma cell lines with CNL of OGG1 or MUTYH, respectively." (PMID 34479993, 2021). "We identified a high contribution of C > A mutational signatures 18 and 36 in the OGG1 and MUTYH knockout clones, respectively, which cluster together with neuroblastoma tumors with OGG1 or MUTYH CNL." (PMID 34479993, 2021). "CNL of MUTYH or OGG1 is common in neuroblastoma since these genes are located on chromosome arms 1p and 3p, respectively, which are recurrently lost in neuroblastoma." (PMID 34479993, 2021). "Our data showed that NMDA indeed elevated the intracellular ROS level in SH-SY5Y neuroblastoma cells, ROS scavenger and OGG1 interference significantly blocked AIF nuclear translocation and cell death." (PMID 29795387, 2018). "Interestingly, increased mutation of the non-transcribed strand was also observed for G > T substitutions in OGG1-/- neuroblastoma cells, indicating that TC-NER can also remove 8-oxoG to help compensate for the absence of BER." (PMID 39715760, 2024). "Therefore, we analyzed WGS data of our neuroblastoma cohort for CNL and mutation status of MUTYH, OGG1, and NUDT1." (PMID 34479993, 2021). "OGG1 is located on 3p.25, which is part of the frequently deleted 3p region in neuroblastoma." (PMID 34479993, 2021). "We also documented OGG1’s role in NMDA-induced parthanatos in SH-SY5Y neuroblastoma cells." (PMID 29795387, 2018). "To validate the correlation between C > A substitutions and defects in the 8-oxoG pathway, we created CRISPR-Cas9 knockout clones of MUTYH, OGG1, or NUDT1 in a neuroblastoma cell line (CHP134)." (PMID 34479993, 2021). "In concordance, knockout of OGG1 and MUTYH results in increased accumulation of C > A substitutions in a neuroblastoma cell line." (PMID 34479993, 2021).
neuroblastoma (continued). "In our cohort of neuroblastoma, signature 18 was also identified as a common signature in a cluster of tumors with frequent CNL of OGG1 or MUTYH (>60% of the tumors)." (PMID 34479993, 2021). "Overall, these results indicate that 8-oxoG levels are increased in neuroblastoma organoids and cell lines with defects in MUTYH and OGG1 and that this can be rescued by overexpression of the affected wild-type gene." (PMID 34479993, 2021).
Stroke (4 papers, 2019 to 2025). Sudden impairment of blood flow to a part of the brain due to occlusion or rupture of an artery to the brain. "After occlusion, a marked increase in 8-oxoG, FapyA, and FapyG levels was detected in both the ipsilateral and the contralateral cortex of WT and OGG1-deficient mice, suggesting that these base lesions are stroke-induced." (PMID 34884729, 2021). "Moreover, it was demonstrated that OGG1-deficient mice had reduced 8-oxoG incision activity both at basal conditions and after stroke." (PMID 34884729, 2021). "Notably, gene polymorphisms in human XRCC1 and OGG1 have been associated with risk for ischemic stroke, suggesting that repair of oxidative damage may be important in the pathogenesis of strokes." (PMID 34884729, 2021). "Deficient DNA repair is closely associated with poor neurological outcomes after stroke, whereas upregulation of specific DNA repair enzymes such as APE1, OGG1, XRCC1, and Gadd45b can enhance long-term functional recovery after stroke." (PMID 39583099, 2024). "Furthermore, a robust increase in OGG1 expression was detected in WT mice shortly after stroke, indicating that a rapid adaptive BER response is essential for neuronal protection." (PMID 34884729, 2021).
viral infection (4 papers, 2018 to 2025). "TH6744 was developed as a part of a compound series targeting OGG1 and considering the link between oxidative stress and virus infection, we investigated the role of OGG1 inhibition on compounds’ antiviral properties." (PMID 33322045, 2020). "As a result, virus infection led to a consistent decrease of OGG1 mRNA levels at 24 and 36 h after infection." (PMID 30049996, 2018). "Thus, OGG1 expression reflects repair mechanisms under conditions of wtTBSV viral infection and combined stress (temperature + virus), and can be considered as one of the molecular markers of the involvement of the BER pathway in the cellular response of plants to oxidative DNA damage." (PMID 41012677, 2025). "The expression of 8-oxoguanine DNA glycosylase (OGG-1), an enzyme responsible for the excision of 8-oxoG, was significantly decreased due to the virus infection, which corroborated with the finding that BoHV-1 infection stimulated 8-oxoG production." (PMID 30049996, 2018). "Indeed, the expression of the OGG1 gene, a key participant in the base excision repair (BER) pathway, increased during viral infection, but was reduced under the combined effect of virus and temperature, indicating variable activity of DNA repair mechanisms depending on the nature of stress." (PMID 41012677, 2025).
Anxiety (3 papers, 2019 to 2023). Intense feelings of nervousness, tension, or panic often arise in response to interpersonal stresses. "In our study, saline-exposed OGG1-deficient males spent more time in the centre without any effect on the total distance travelled, suggesting reduced fear and anxiety in OGG1-deficient males, which was not significantly altered in EtOH-exposed Ogg1 −/− males." (PMID 37759530, 2023). "Our results suggest that anxiety-like behaviour may be both an OGG1- and sex-dependent effect of EtOH, and may involve mechanisms such as estrogen receptors and the interaction between OGG1- and ESR-mediated gene regulation." (PMID 37759530, 2023). "Lack of Ogg1 and Mutyh was reported to upregulate ERα target-genes, which in turn modulated cognition and anxiety-like behavior in mice." (PMID 31784530, 2019). "In contrast, with in utero EtOH exposure, although the total distance travelled in Ogg1 +/+ and −/− females was unaffected, the time spent in the centre zone was decreased in Ogg1 +/+ but not −/− females, suggesting that the EtOH-mediated increased fear and anxiety was OGG1-dependent." (PMID 37759530, 2023). "In this context, it has been shown that mice lacking the DNA glycosylases OGG1 and MUTYH — upstream enzymes involved in BER responsible for removing damaged bases — show a decrease in anxiety and impaired learning ability, potentially due to altered hippocampal gene expression." (PMID 35907861, 2022).
endometriosis (3 papers, 2015 to 2025). The growth of functional endometrial tissue in anatomic sites outside the uterine body. "OGG1 has been implicated in the pathophysiology of several obstetric and gynecological diseases, including polycystic ovary syndrome, endometriosis, preeclampsia, preterm birth, and gynecologic cancers." (PMID 40813502, 2025). "Given the involvement of NF-κB, dysregulated angiogenesis, apoptosis, and autophagy in the pathophysiology of endometriosis, it can be inferred that OGG1 may promote inflammation and autophagy while inhibiting angiogenesis." (PMID 40813502, 2025). "This review aims to synthesize current knowledge primarily on non-canonical functions of OGG1, with a focus on its potential involvement in disorders such as endometriosis, polycystic ovary syndrome, uterine fibroids, and malignancies, and to highlight its promise as a therapeutic target." (PMID 40813502, 2025).
gallbladder cancer (3 papers, 2012 to 2016). "Multiple polymorphisms in genesassociated with the immune system, inflammation, and oxidative stress that have been linkedto the development of gallbladder cancer like PTGS2, TLR2, TLR4, IL1RN, IL10, IL8, CCR5,LXRB, and OGG1." (PMID 28105075, 2016).
glioblastoma (3 papers, 2009 to 2021). The most malignant astrocytic tumor (WHO grade IV). "While exposure to acute hypoxia decreased expression of BER genes MTH1, OGG1 and FEN1, we did not observe differences in the expression of these genes between anoxia-tolerant and oxic control NCI-H460 lung or T98G glioblastoma cancer cells in acute hypoxic conditions." (PMID 34831264, 2021).
Hepatic steatosis (3 papers, 2012 to 2017). Steatosis is a term used to denote lipid accumulation within hepatocytes. "OGG1-deficient (Ogg1−/−) mice have increased adiposity and hepatic steatosis following exposure to a high-fat diet (HFD), compared to wild-type (WT) animals." (PMID 23284747, 2012). "Furthermore, synthesis of reactive oxygen species and hydrogen peroxide was activated in Ogg1−/− mouse HCCs, while inflammation and hepatic steatosis were predicted to be increased in the livers of Ogg1−/− mice treated with PB." (PMID 28785378, 2017).
Impaired glucose tolerance (3 papers, 2012 to 2019). An abnormal resistance to glucose, i.e., a reduction in the ability to maintain glucose levels in the blood stream within normal limits following oral or intravenous administration of glucose. "Ogg1−/− animals also have higher plasma insulin levels and impaired glucose tolerance upon HFD feeding, relative to WT counterparts." (PMID 23284747, 2012).